TGFB2 (transforming growth factor beta 2)
Diseases named in the same sentence as TGFB2 in open-access papers (continued):
Sharing a sentence is not in itself a finding about the gene and the disease.
glioma (continued). "In support to this notion, TGFβ2 was previously attributed a dominant role in predicting the outcome of breast cancers and aberrant expression of the TGFβ2 isoform exclusively was induced through an autocrine loop in glioma." (PMID 28915803, 2017). "However, the precise molecular mechanisms of the cross-talk between TAGLN2 and TGFβ2 signaling in gliomas require further investigation." (PMID 29110682, 2017). "However, the relative involvement of Smad2 and Smad3 in the control of TGFβ2-induced cell proliferation in glioma cells remains to be elucidated." (PMID 25891822, 2015). "Though MCODE was able to identify genes such as TGFB2, a putative glioma tumour regulator and drug target, they were mostly included in modules that displayed very low statistical significance (B-score close to 1), indicating a high likelihood of statistical artifacts." (PMID 24523864, 2014). "The most advanced is a phosphorothioate-modified AS-ODN (Trabedersen, AP 12009, Antisense pharma) directed against the transforming growth factor-beta 2 (TGF-β2), a protein that is massively produced by high-grade gliomas and promotes tumor cell proliferation, angiogenesis, invasion and metastasis." (PMID 22685651, 2012). "Based on these studies and the results of the present study, we hypothesized that the differences in the molecular structures of Smad2 and Smad3 may be the reason underlying why Smad3 has a significant effect on the regulation of TGFβ2-induced cell proliferation in glioma cells." (PMID 25891822, 2015). "Given the important roles of TGFB ligands and IFN-γ released by immune cells in the TME as related to IDH mutational status, we tested the clinical prognostic significance of high tumor TGFB2 and IFNGR2 mRNA levels measured in low-grade gliomas." (PMID 38539537, 2024). "In this study, we also showed that LAIR1 remarkably promoted the production of CCL5, TGFβ2, and IL33 in glioma cells, in a nuclear FAK-dependent manner." (PMID 37845206, 2023). "In the next part of the study, changes in the expression levels of TGFβ1, TGFβ2, TGFβ3, and ACTB were evaluated in gliomas with different degrees of malignancy." (PMID 35454784, 2022). "This combined network linked both PRKG1 and CFTR to genes already known to be of importance in glioma biology such as PDGFRA, met, and TGFβ2, amongst others." (PMID 27564115, 2016). "Integrated DNA and RNA analysis of low-grade and high-grade proneural gliomas identified increased expression and gene amplification of several genes including GLIS3, TGFB2, TNC, AURKA, and VEGFA in proneural GBMs, with corresponding loss of DLL3 and HEY2." (PMID 20838435, 2010). "miR-328 suppresses the survival of cancer cells by targeting PLCE1 in esophageal cancer, inhibits epithelial to-mesenchymal transition in renal tubular cells by targeting CD44, and regulates cell invasion and proliferation in glioma cells by targeting SFRP1 and in melanoma cells by targeting TGFb2." (PMID 29374351, 2018). "Bioinformatic analysis of transforming growth factor beta 2 (TGFB2) mRNA has revealed its significant role as a negative prognostic marker in low-grade glioma, where mRNA levels of TGFB2 are upregulated in low-grade glioma (LGG) tumors and correlated with poorer overall survival outcomes." (PMID 40338274, 2025). "While the DIPG patients were younger than the non-DIPG DMG patients, no age-related changes in the TGFB2 responsiveness of high-grade pediatric glioma cells or tumor microenvironment composition in DMG have been reported to suggest the observations were in part age-related." (PMID 36980562, 2023). "In a recent study that employed a microarray-based gene expression platform, we found that TGFB2 mRNA levels were selectively amplified in primary tumor samples from 29 pediatric DIPG patients compared to normal samples and primary tumor samples from low-grade glioma patients." (PMID 36980562, 2023).
glioma (continued). "miR-142-3p is downregulated in glioblastoma-infiltrating macrophages, which contribute to the glioma growth probably by promoting M2-like TAM apoptosis through targeting transforming growth factor beta receptor 1 (TGFBR1) and transforming growth factor beta 2 (TGFB2)." (PMID 29899293, 2018). "In addition, TGFβ2 induces the expression of MMP2 in glioma cells and suppresses the expression of tissue inhibitor of metalloproteinases (TIMP)-2, which degrades the extracellular matrix and subsequently promotes glioma invasion." (PMID 29410971, 2017).
breast cancer (87 papers, 2009 to 2026). A primary or metastatic malignant neoplasm involving the breast. "For TGFB2-dependent biomarkers, elevated TGFB2 mRNA expression is a prognostic biomarker associated with breast cancer patients that is correlated with improved OS outcomes at high expression levels of GDAP1, TBL1XR1, RNFT1, HACL1, SLC27A2, NLE1, and TXNDC16." (PMID 41373732, 2025). "It is noted that the TGFB2 association represents a strong correlation; future controlled experiments in reduced systems will be required to infer mechanistic insight of this TGFB2 association in breast cancer tissues." (PMID 41373732, 2025). "The levels of TGFβ1 (≥46,713 pg/mL) and TGFβ2 (between 1005 and 2998 pg/mL) showed increasing O.R.s for breast cancer risk in LA only." (PMID 38541912, 2024). "Our study identified serum levels of MIP-1b/CCL4, TGFβ1, and TGFβ2 were independently associated with breast cancer." (PMID 38541912, 2024). "αvβ3 integrin has been shown to be associated with the upregulation of TGFB2 in several cell types including a breast cancer epithelial cell line and human skin fibroblasts." (PMID 34440692, 2021). "On the other hand, as previously discussed, we know from other reports that higher expression of KLK 6, 8, 10 and TGFβ2 have been associated with a lower risk of breast cancer." (PMID 22436421, 2012). "The association of MIP-1b/CCL4, TGFβ1, and TGFβ2 and breast cancer were complicated." (PMID 38541912, 2024). "In breast cancer, a novel functional polymorphism in TGFβ2 gene promoter could enhance TGFβ2 expression levels in vivo and therefore contribute to the tumor progression and the development of metastases." (PMID 33115518, 2020). "To further gain insight into association of miR-191 and TGFβ-pathway in the promotion of breast cancer migration, we examined whether the silencing/restoration of TGFβ2 affects miR-191 induced cell migration." (PMID 25867965, 2015). "Also, we found weak expression of OCLN and strong expression of TGFβ2, an association which was previously demonstrated to be linked to the breast cancer epithelial mesenchymal transition (EMT)." (PMID 21858074, 2011). "Examination of the protein–protein interaction networks suggested that the correlation of TGFB2-related markers could potentially complement the PAM50 signature in the assessment of OS prognosis in breast cancer patients following validation of the TGFB2/EGFR/MYC protein associations in tumors." (PMID 41373732, 2025). "We evaluated the impact of TGFB2 mRNA expression, in conjunction with other potential prognostic markers, on overall survival (OS) in breast cancer patients using The Cancer Genome Atlas (TCGA) and KMplotter databases." (PMID 41373732, 2025). "Protein–protein interaction (STRING) analysis indicated that TGFB2 is associated with EGFR and MYC from the PAM50 breast cancer gene signature." (PMID 41373732, 2025). "Within the micrometastatic bone marrow niche, NG2+/Nestin+ MSCs induce dormancy of disseminated breast cancer cells via TGFβ2 and BMP7; conversely, MSC depletion or TGFβ2 knockout in MSCs reactivates dormant cells." (PMID 41020040, 2025). "and that the addition of HDAC inhibitors to breast cancer cell lines blocked the expression of TGFβ2." (PMID 39992949, 2025). "In our multivariate Cox proportional hazards model, increasing levels of SULF1 increased the HR in breast cancer patients (22% increase for one standard deviation increase in gene expression), in contrast to the positive prognostic impact of TGFB2 mRNA levels." (PMID 41373732, 2025). "This analysis was controlled for age at diagnosis, breast cancer subtype, treatment (chemotherapy-only (chemo-only) versus all other treatments), and the interaction between TGFB2 by Gene2 for 786 evaluable patients." (PMID 41373732, 2025). "This analysis was controlled for age at diagnosis, breast cancer subtype, the confounding effect of treatment (chemo-only versus all other treatments), and the interaction between TGFB2 and Gene2." (PMID 41373732, 2025).
breast cancer (continued). "We utilized a bioinformatic-driven approach to characterize the impact of TGFB2 mRNA, in combination with potential prognostic markers, on overall survival in breast cancer patients from The Cancer Genome Atlas (TCGA) database." (PMID 41373732, 2025). "The interaction term in the model enabled the identification of TGFB2/Gene2 mRNA combinations that result in synergistic improvements for breast cancer patients." (PMID 41373732, 2025). "Overexpression of TGFβ2 reversed the inhibitory effect of ezetimibe on the migration and invasion of breast cancer cells." (PMID 38531630, 2024). "Numerous studies have indicated that TGFβ2 facilitates breast cancer metastasis by promoting EMT and lipid storage in tumor cells." (PMID 38531630, 2024). "Multiple studies have demonstrated that increased expression of TGFβ2 promotes breast cancer metastasis." (PMID 38531630, 2024). "Two other studies in breast cancer also showed that inhibition of TGFB2 expression can maintain tumor sensitivity to chemotherapy." (PMID 38914663, 2024). "Previous reports have highlighted the significant role of the TGF-β pathway in promoting angiogenesis and progression in breast cancer by inducing EndMT, thereby clarifying the promotive effect of the TGFB2-TGFBR2 on APOC1+ TAMs in tumor progression." (PMID 39232806, 2024). "To investigate how ezetimibe can impede TGFβ2 expression in breast cancer cells, we conducted RNA‐Seq experiments on drug‐treated cells." (PMID 38531630, 2024). "The expression of miR-592 is significantly decreased in breast cancer and inversely correlates to the proto-oncogene TGFβ2 expression." (PMID 33498521, 2021). "In breast cancer cells, overexpressing ci-miRNA-191, was associated with upregulated levels of TGF-β pathway genes (TGFβ2, SMAD3, BMP4, JUN, FOS, PTGS2, CTGF, and VEGFA), thus promoting breast cancer growth and metastasis." (PMID 32942528, 2020). "Recently, a number of lncRNAs were documented to be associated with TGFß signaling pathway, including MEG3 regulating the TGFB2 pathway in breast cancer." (PMID 30642353, 2019). "TGFβ2 has been proposed as a predictive marker for breast cancer, as high levels of TGFβ2 correlate with advanced tumor stage and shortened survival." (PMID 28915803, 2017). "Although the role of TGFβ isoforms in tumors remains debatable, most studies that focus on exosomal TGFβ report that TGFβ1 enhances EMT in diverse cancer models, and TGFβ2 in milk exosomes drives breast cancer cells towards EMT." (PMID 29221185, 2017). "Altogether, TRAP promotes metastasis-related cell properties in MDA-MB-231 breast cancer cells via TGFβ2/TβR and CD44, thereby identifying a potential signaling mechanism associated to TRAP action in breast cancer cells." (PMID 28915803, 2017). "Taken together, these findings suggest that hypoxia induced miR-191 increases breast cancer cell migration through TGFβ2 induction in a SMAD3-dependent manner." (PMID 25867965, 2015). "What is more, the dysregulated genes IL2RG, IL6R, IL7R and TGFB2 have been reported to be associated with metastasis site or prognosis, and CCR6 is associated with both live metastasis in breast cancer and bone metastasis in human neuroblastoma." (PMID 25163697, 2014). "Specifically in the context of breast cancer, resveratrol inhibits TGFα resulting in the elevated expression of TGFβ2." (PMID 23840623, 2013). "DAB2 expression is also reduced in breast cancer, which results in up-regulation of TGFβ2 that promotes EMT transition." (PMID 23213280, 2012). "The involvement of some of the genes affecting cancer cell death–Adm, Cflar, Cyr61, Ddit4, Itgb1, Mapk1, Mapk8, Tgfβ2, Tpm1, Vegfα and Wasf1, was demonstrated in breast cancer cell lines." (PMID 19450255, 2009).
breast cancer (continued). "Our analysis revealed a novel positive TGFB2-dependent effect of these Gene2 markers on breast cancer survival, whereas previous studies on the expression of these TGFB2-dependent genes focused solely on their impact on either the risk score or as negative prognostic biomarkers." (PMID 41373732, 2025). "This correlation suggests that TGFB2 mRNA expression levels in breast cancer tumors may be used in conjunction with the PAM50 gene signature to assess the prognostic impact on patients following validation in prospective clinical trials." (PMID 41373732, 2025). "We have now extended these studies to examine the role of TGFB2 mRNA in breast cancer prognosis." (PMID 41373732, 2025). "Our studies indicated that the prognostic impact was TGFB2 mRNA-dependent using both the Cox proportional hazards model and the Kaplan–Meier analysis, suggesting that breast cancer patients with high levels of both TGFB2 and GDAP1 expression displayed significantly improved OS outcomes." (PMID 41373732, 2025). "Future studies will be required to confirm breast cancer patients could improve OS outcomes for patients expressing high levels of TGFB2 and the marker genes in prospective clinical trials." (PMID 41373732, 2025). "Finally, breast cancer cells overexpressing TGFβ2 were constructed, and the effect of TGFβ2 on the migration and invasion of ezetimibe‐treated breast cancer cells was examined." (PMID 38531630, 2024). "Similarly, our data revealed that ezetimibe restrains breast cancer cell migration and invasion, conceivably by targeting TGFβ2 and its downstream target PI3K/AKT pathway." (PMID 38531630, 2024). "TGFβ1 and TGFβ2 were also more likely to increase OR for breast cancer in LA women." (PMID 38541912, 2024). "Moreover, in silico meta-analysis of JUNB protein levels showed its association with poor survival in breast cancer patients and identified a positive correlation between JUNB, CCNE1, and TGFB2 expression levels in these tumors." (PMID 36494864, 2022). "SRGN/TGFβ2 interlay establishes a positive feedback loop that promotes EMT in breast cancer cells." (PMID 36358747, 2022). "In addition, the transforming growth factor-beta 2 (TGF-β2)/ANGPTL4 axis was reported to be responsible for breast cancer brain metastasis in a mouse model." (PMID 33726754, 2021). "For instance, in breast cancer cells, milk exosomes containing high levels of TGFβ2 promote EMT." (PMID 31564251, 2019). "Furthermore, the regulation of TGFβ2 by IGF-I was confirmed in other breast cancer cell lines (MCF-7L, MCF-7ATCC, MDA-231 and F11) as measured by qPCR, but not in the normal MCF10A cells." (PMID 26991655, 2016). "miR-191 mediated TGFβ2 induction promotes breast cancer cell migration." (PMID 25867965, 2015). "In addition, AKT directly phosphorylates TWIST1 at Ser42 to promote TWIST1-mediated expression of TGFβ2, leading to enhanced TGFβ signaling in breast cancer cells." (PMID 26204939, 2015). "Thus, results obtained from all the three cell lines suggest that miR-191 mediated breast cancer migration under hypoxia is TGFβ2 dependent." (PMID 25867965, 2015). "Although detailed molecular mechanisms by which cytoplasmic maspin activates SRGN/TGFβ2 axis remain to be clarified, our data suggest that cytoplasmic maspin plays a pivotal role in the aggressive phenotype and serves as a therapeutic target in patients with breast cancer, especially TNBC." (PMID 34059749, 2021). "Most importantly, we identified a regulation of the TGFβ pathway-associated proteins TGFβ2, TβR1 and SMAD2, as well as a highly significant upregulation of previously unreported phosphorylation sites of CD44 upon TRAP perturbation in the MDA-MB-231 breast cancer cell line." (PMID 28915803, 2017). "Therefore, IGF-induced TGFβ2 expression drives cell motility in MCF7 breast cancer cells." (PMID 26991655, 2016).